CCNT2 (cyclin T2)
Description:
Regulatory subunit of the cyclin-dependent kinase pair (CDK9/cyclin T) complex, also called positive transcription elongation factor B (P-TEFB), which is proposed to facilitate the transition from abortive to production elongation by phosphorylating the CTD (carboxy-terminal domain) of the large subunit of RNA polymerase II (RNAP II). The activity of this complex is regulated by binding with 7SK snRNA. Plays a role during muscle differentiation; P-TEFB complex interacts with MYOD1; this tripartite complex promotes the transcriptional activity of MYOD1 through its CDK9-mediated phosphorylation and binds the chromatin of promoters and enhancers of muscle-specific genes; this event correlates with hyperphosphorylation of the CTD domain of RNA pol II (By similarity). In addition, enhances MYOD1-dependent transcription through interaction with PKN1. Involved in early embryo development (By similarity). (Microbial infection) Promotes transcriptional activation of early and late herpes simplex virus 1/HHV-1 promoters.
Synonyms: CycT2
Tractability: Small molecule: a high-quality ligand is known. Antibody: the Human Protein Atlas places it where antibodies can reach. PROTAC: UniProt records ubiquitination sites on it; ubiquitination databases record sites on it; its protein half-life has been measured; a small molecule that binds it is known.
Target class: Kinase; Protein kinase regulatory subunit; Enzyme
Gene: Protein-coding gene on chromosome 2 (134,918,235 to 134,959,342, forward strand). Ensembl gene ENSG00000082258.
Subcellular location: Cytoplasm, perinuclear region; Nucleus
Subcellular location (Human Protein Atlas): Cytosol; Nucleoplasm; Plasma membrane
Pathways (Reactome):
Gene expression (Transcription): Formation of RNA Pol II elongation complex; RNA Polymerase II Pre-transcription Events; RNA Polymerase II Transcription Elongation; RNA polymerase II transcribes snRNA genes
Disease: Formation of HIV elongation complex in the absence of HIV Tat; HIV elongation arrest and recovery; Pausing and recovery of HIV elongation
Signal Transduction: SMAD2/SMAD3:SMAD4 heterotrimer regulates transcription
Gene Ontology:
Molecular function: 7SK snRNA binding; protein binding; RNA polymerase binding; transcription coactivator binding; chromatin binding; cyclin-dependent protein serine/threonine kinase activator activity; cyclin-dependent protein serine/threonine kinase regulator activity
Biological process: early viral transcription; late viral transcription; positive regulation of transcription by RNA polymerase II; positive regulation of DNA-templated transcription, elongation; regulation of cyclin-dependent protein serine/threonine kinase activity; transcription by RNA polymerase II; positive regulation of transcription elongation by RNA polymerase II; regulation of transcription by RNA polymerase II; skeletal muscle tissue development
Cellular component: cyclin/CDK positive transcription elongation factor complex; nucleus; nucleoplasm; perinuclear region of cytoplasm
Genetic constraint (gnomAD): Loss-of-function variants: 10 observed, 39.61 expected, observed/expected ratio (o/e) 0.25, 90% interval 0.16 to 0.43. The upper end of that interval is the gene's LOEUF score, 0.43, which puts it in group 1 of 6, group 1 being the genes least tolerant of losing a copy. Missense variants: 613 observed, 714.39 expected, observed/expected ratio (o/e) 0.86, 90% interval 0.8 to 0.92. Synonymous variants: 271 observed, 260.07 expected, observed/expected ratio (o/e) 1.04, 90% interval 0.94 to 1.15.
Homologues: Orthologues: chimpanzee CCNT2 (99% identical), macaque CCNT2 (97% identical), dog CCNT2 (95% identical), guinea pig CCNT2 (93% identical), rabbit CCNT2 (91% identical), pig CCNT2 (89% identical), mouse Ccnt2 (87% identical), rat Ccnt2 (86% identical), tropical clawed frog ccnt2 (65% identical), zebrafish ccnt2a (55% identical), zebrafish ccnt2b (47% identical), Drosophila melanogaster CycT (28% identical), and 2 more. Paralogues in human: CCNT1 (46% identical), CCNL1 (18% identical), CCNK (18% identical), CCNL2 (16% identical), CCNH (11% identical), CCNQ (7% identical).
Diseases named in the same sentence as CCNT2 in open-access papers:
CCNT2 is named in the same sentence as 14 diseases in open-access papers, as found by Europe PMC text mining. Sharing a sentence is not in itself a finding about the gene and the disease. The quoted sentences say what the papers report.
gastric cancer (5 papers, 2020 to 2023). A primary or metastatic malignant neoplasm involving the stomach. "Cyclin T2 is another type of Cyclin, and has been observed in gastric cancer samples in overexpressed form as compared to normal counterparts." (PMID 36769170, 2023). "Cyclin T2 overexpression reversed the effects of miR-216b mimicking effects in experiments on gastric cancer cells, implicating a mechanism of Cyclin T2 regulation in the development of gastric cancer." (PMID 36769170, 2023). "A previous study stated that miR-142-3p may play a suppressor role in the development of gastric cancer via downregulating CCNT2." (PMID 33817287, 2020).
acute myeloid leukemia (3 papers, 2020 to 2022). Acute myeloid leukemia (AML) is a group of neoplasms arising from precursor cells committed to the myeloid cell-line differentiation. "Cyclin T2 (CCNT2) is a protein coding gene, and is highly associated with diverse diseases, such as myocardial ischemia reperfusion injury, acute myeloid leukemia and chronic kidney disease." (PMID 35012431, 2022). "Previous research has revealed the involvement of microRNA-212-5p (miR-212-5p) and cyclin T2 (CCNT2) in acute myeloid leukemia (AML)." (PMID 33817287, 2020). "While there are no data on CCNT2 in CML, it was shown to be overexpressed in acute myeloid leukemia and to promote proliferation in this cancer." (PMID 34316716, 2021).
breast carcinoma (2 papers, 2020 to 2021). "Cyclin T2 (CCNT2) and acyl-CoA synthetase long-chain family member 5 (ACSL5) are involved with breast cancer." (PMID 34497631, 2021).
viral infection (2 papers, 2020). "Reflecting a potential general role in viral infection, appreciable intersections were observed between the CCNT2 HCTs and all viral HCTs (q-values: SARS1, 4e-4; SARS2, 6e-3; MERS, 7e-5)." (PMID 32511379, 2020).
hepatocellular carcinoma (1 paper, 2025). A malignant tumor that arises from hepatocytes. "One more strategy used nanoparticles to silence circROBO1 and regulate the miR-130a-5p/CCNT2 axis to inhibit the progression of hepatocellular carcinoma." (PMID 41299798, 2025).
HIV-1 infection (1 paper, 2012). The type species of lentivirus and the etiologic agent of acquired immunodeficiency syndrome (AIDS). "However, CCNT1 but not CCNT2 expression can be up-regulated in late differentiated macrophage by either HIV-1 infection or activation with pathogen-associated molecular patterns (PAMPs)." (PMID 23110726, 2012).
intrauterine growth retardation (1 paper, 2024). "Epigenetic changes have also been identified in human adipose-derived stem cells from infants with intrauterine growth retardation (IUGR) resulting in a down-regulation of CYCLIN-T2 expression, a gene controlling adipose maturation that confers risk of abnormal lipid metabolism." (PMID 39377073, 2024).
laryngeal papilloma (1 paper, 2022). "The aim of the present study was to explore the expression levels of Lnc-NEAT1, miR-577, miR-1224-5p and CCNT2 in LP, and to further investigate the potential underlying molecular mechanism by which they regulate the progress of laryngeal papilloma development." (PMID 35012431, 2022).
leukemia (1 paper, 2021). A malignant (clonal) hematologic disorder, involving hematopoietic stem cells and characterized by the presence of primitive or atypical myeloid or lymphoid cells in the bone marrow and the blood. "We set the cutoff of the signal binding normalized scores (in the range of 0–1000) to 350 and identified promyelocytic leukemia (PML), cyclin T2 (CCNT2) and MYC-associated zinc finger protein (MAZ) as binding to both the +157 enhancer and the promoter of the VEGFA gene." (PMID 34316716, 2021).
cancer (5 papers, 2016 to 2021). A tumor composed of atypical neoplastic, often pleomorphic cells that invade other tissues. "In addition, this polymorphism affects binding to 5 proteins implicated in cancer development (CCNT2, GATA2, TAL1, KAP1 and CTCF)." (PMID 27437873, 2016). "The increased expression of MAPK1, which is upregulated by transcription factor CCNT2 and affected by DNA methylation, can lead to the growth and migration of tumor cells and initiate mitotic function to induce the cancer cell cycle." (PMID 31126066, 2019). "The expression level of the cell cycle regulators (i.e. CCNT2 and CCNA2) has been linked to cell cycle progression and cancer growth." (PMID 30944375, 2019). "As shown by GSCA, except CCNY, CCNT2, and CCNC, all cyclin genes were differentially expressed in different cancers, among which the number of genes in COAD was the highest, with 16 genes differentially expressed in total." (PMID 33996604, 2021).
tumor (3 papers, 2007 to 2022). "Both genes, KIAA0256 in the "protein biosynthesis" pathway and CCNT2 in the "cell cycle pathway", were associated with an aggressive tumor behavior." (PMID 17894856, 2007). "Although the functional role of Lnc-NEAT1/miR-577 or miR-1224-5p/CCNT2 axis in LP has been identified, the regulatory role in tumor growth in vivo remains to be validated in further studies." (PMID 35012431, 2022).
cardiovascular diseases (1 paper, 2011). "Cyclin T2 specific genes were over represented only in the aging process while metabolic and cardiovascular diseases were linked to genes that were commonly down-regulated upon Cyclin T2 or Cyclin T1 depletion." (PMID 21791050, 2011).
CCNT2 also shares sentences with these, for which no sentence is quoted: chronic kidney disease (1 paper); osteosarcoma (1).